TMEM87A (transmembrane protein 87A)
Description:
Voltage- and pH-dependent, inwardly rectifying cation channel that mediates ion flux across the Golgi membrane, supporting luminal acidification necessary for normal Golgi morphology and function. Implicated in normal touch sensitivity through the generation of mechanically activated currents. Could also be involved in cell mechanosensitivity regulating cell adhesion and migration. May also be involved in retrograde transport from endosomes to the trans-Golgi network (TGN). Contributes to hippocampal spatial and contextual memory by maintaining Golgi function and structural integrity in hippocampal neurons (By similarity).
Synonyms: GOLPHCAT; DKFZP564G2022; ELKIN1
Tractability: Small molecule: a structure with a bound ligand is known. Antibody: UniProt places it where antibodies can reach, with high confidence; its Gene Ontology location is reachable by antibodies, with high confidence; UniProt predicts a signal peptide or a membrane-spanning region. PROTAC: ubiquitination databases record sites on it; its protein half-life has been measured.
Gene: Protein-coding gene on chromosome 15 (42,210,447 to 42,274,128, reverse strand). Ensembl gene ENSG00000103978.
Subcellular location: Cell membrane (Isoform 1); Golgi apparatus membrane; Cell membrane (Isoform 3); Cell projection, ruffle
Subcellular location (Human Protein Atlas): Golgi apparatus
Pathways (Reactome):
Signal Transduction: RHOA GTPase cycle
Gene Ontology:
Molecular function: mechanosensitive potassium channel activity; voltage-gated monoatomic anion channel activity
Biological process: cellular response to mechanical stimulus; detection of mechanical stimulus involved in sensory perception of touch; intracellular pH reduction; retrograde transport, endosome to Golgi; monoatomic anion transmembrane transport
Cellular component: Golgi apparatus; Golgi cisterna membrane; Golgi membrane; plasma membrane; cytosol; membrane; ruffle
Genetic constraint (gnomAD): Loss-of-function variants: 37 observed, 70.14 expected, observed/expected ratio (o/e) 0.53, 90% interval 0.41 to 0.69. The upper end of that interval is the gene's LOEUF score, 0.69, which puts it in group 2 of 6, group 1 being the genes least tolerant of losing a copy. Missense variants: 477 observed, 571.92 expected, observed/expected ratio (o/e) 0.83, 90% interval 0.77 to 0.9. Synonymous variants: 200 observed, 208 expected, observed/expected ratio (o/e) 0.96, 90% interval 0.86 to 1.08.
Homologues: Orthologues: chimpanzee TMEM87A (99% identical), macaque TMEM87A (98% identical), rabbit TMEM87A (96% identical), dog TMEM87A (95% identical), pig TMEM87A (94% identical), mouse Tmem87a (93% identical), guinea pig TMEM87A (90% identical), rat Tmem87a (89% identical), tropical clawed frog tmem87a (67% identical), Drosophila melanogaster CG17660 (39% identical), Caenorhabditis elegans C52B9.4 (32% identical), Drosophila melanogaster CG12121 (15% identical), and 1 more. Paralogues in human: TMEM87B (46% identical), GPR107 (17% identical), GPR108 (16% identical).
Diseases named in the same sentence as TMEM87A in open-access papers:
TMEM87A is named in the same sentence as 13 diseases in open-access papers, as found by Europe PMC text mining. Sharing a sentence is not in itself a finding about the gene and the disease. The quoted sentences say what the papers report.
melanoma (7 papers, 2020 to 2026). A malignant, usually aggressive tumor composed of atypical, neoplastic melanocytes. "Later in 2020, a study found that the mechanically activated currents in melanoma cells are associated with TMEM87A, and expression of TMEM87A induced robust mechanosensitive currents in PIEZO1-KO HEK293 cells." (PMID 37508534, 2023). "Depletion of TMEM87A leads to Golgi overacidification, which impairs FSP1-mediated reduction of coenzyme Q. In vivo, TMEM87A ablation suppresses the progression of multiple murine tumors including melanoma, colorectal cancer and liver cancer." (PMID 42014864, 2026). "TMEM87a/Elkin1 modulates cellular adhesions, melanoma cell migration and cell-cell interactions through the PIEZO1-independent mechanoelectrical transduction pathway." (PMID 39817348, 2025). "TMEM87A has been proven to modulate melanoma adhesion and migration as a component of a novel mechanoelectrical transduction pathway." (PMID 38886500, 2024). "Deflection of micropillar culture supports resulted in cationic currents in melanoma cells that were reduced by TMEM87A expression knockdown." (PMID 36373655, 2022). "TMEM87A knockout melanoma cells show increased adhesion strength and decreased migration, suggesting potential roles for TMEM87A in these processes in cancers." (PMID 36373655, 2022). "We describe here the presence of mechanically activated currents in melanoma cells that are dependent on TMEM87a, which we have renamed Elkin1." (PMID 32228863, 2020). "Therefore, if a mechanosensitive channel truly exists in melanoma cells, TMEM87A may promote its trafficking to the plasma membrane though it is not specifically involved in this mechano-transduction pathway." (PMID 37508534, 2023).
dilated cardiomyopathy (1 paper, 2024). Cardiomyopathy which is characterized by dilation and contractile dysfunction of the left and right ventricles. "By integrated bioinformatic analyses, TMEM87A was also identified as target genes and transcription factors in mice with dilated cardiomyopathy." (PMID 38886500, 2024).
gastric cancer (1 paper, 2024). A primary or metastatic malignant neoplasm involving the stomach. "In addition, TMEM87A could promote metastasis of gastric cancer and cell proliferation by elevating ULK1 via sponging miR-142-5p29." (PMID 38886500, 2024).
heart failure (1 paper, 2024). Inability of the heart to pump blood at an adequate rate to meet tissue metabolic requirements. "TMEM87A, PPP2R2A, DUSP1, and miR-92a have great potential as biomarkers for heart failure." (PMID 38886500, 2024).
cancer (5 papers, 2020 to 2026). A tumor composed of atypical neoplastic, often pleomorphic cells that invade other tissues. "Our study reveals that TMEM87A functions as a suppressor of tumoral ferroptosis by maintaining Golgi pH homeostasis and targeting TMEM87A is potent to augment cancer immunotherapy." (PMID 42014864, 2026). "Both TMEM87A and TMEM87B have additionally been implicated in cancers such as non-small cell lung cancer through fusion or suspected interaction with oncogenes." (PMID 36373655, 2022).
tumor (3 papers, 2020 to 2026). "In vivo, CHP1 or TMEM87A knockout significantly suppressed orthotopic tumor growth and metastasis in NSG mice, indicating a role in overall tumor progression beyond metastasis alone." (PMID 42258092, 2026).
TMEM87A also shares sentences with these, for which no sentence is quoted: acute myeloid leukemia (1 paper); Anxiety (1); colorectal cancer (1); Hypertension (1); liver cancer (1); melanocytic neoplasm (1); memory impairment (1).